PCLO (piccolo presynaptic cytomatrix protein)
Description:
Scaffold protein of the presynaptic cytomatrix at the active zone (CAZ) which is the place in the synapse where neurotransmitter is released (By similarity). After synthesis, participates in the formation of Golgi-derived membranous organelles termed Piccolo-Bassoon transport vesicles (PTVs) that are transported along axons to sites of nascent synaptic contacts (By similarity). At the presynaptic active zone, regulates the spatial organization of synaptic vesicle cluster, the protein complexes that execute membrane fusion and compensatory endocytosis (By similarity). Organizes as well the readily releasable pool of synaptic vesicles and safeguards a fraction of them to be not immediately available for action potential-induced release (By similarity). Also functions in processes other than assembly such as the regulation of specific presynaptic protein ubiquitination by interacting with SIAH1 or the regulation of presynaptic autophagy (By similarity). Also mediates synapse to nucleus communication leading to reconfiguration of gene expression by associating with the transcriptional corepressor CTBP1 and by subsequently reducing the size of its pool available for nuclear import (By similarity).
Synonyms: ACZ; KIAA0559; DKFZp779G1236; PCH3
Tractability: Small molecule: it has a binding pocket of medium quality. Antibody: the Human Protein Atlas places it where antibodies can reach. PROTAC: ubiquitination databases record sites on it; its protein half-life has been measured.
Gene: Protein-coding gene on chromosome 7 (82,754,012 to 83,162,930, reverse strand). Ensembl gene ENSG00000186472.
Subcellular location: Presynaptic active zone
Subcellular location (Human Protein Atlas): Plasma membrane; Nuclear speckles
Pathways (Reactome):
Sensory Perception: Sensory processing of sound by inner hair cells of the cochlea
Gene Ontology:
Molecular function: protein binding; calcium ion binding; calcium-dependent phospholipid binding; profilin binding; structural constituent of presynaptic active zone; metal ion binding
Biological process: cytoskeleton organization; presynaptic active zone assembly; protein localization to synapse; synaptic vesicle exocytosis; maintenance of presynaptic active zone structure; presynapse organization; presynaptic actin cytoskeleton organization; regulation of transport; synaptic vesicle clustering
Cellular component: extracellular exosome; axon; cytoskeleton; cytoskeleton of presynaptic active zone; GABA-ergic synapse; glutamatergic synapse; presynaptic active zone; synapse; organelle; postsynaptic density
Genetic constraint (gnomAD): Loss-of-function variants: 55 observed, 360.95 expected, observed/expected ratio (o/e) 0.15, 90% interval 0.12 to 0.19. The upper end of that interval is the gene's LOEUF score, 0.19, which puts it in group 1 of 6, group 1 being the genes least tolerant of losing a copy. Missense variants: 5,662 observed, 5,765.9 expected, observed/expected ratio (o/e) 0.98, 90% interval 0.96 to 1. Synonymous variants: 2,161 observed, 2,058.2 expected, observed/expected ratio (o/e) 1.05, 90% interval 1.01 to 1.09.
Homologues: Orthologues: chimpanzee PCLO (99% identical), macaque PCLO (97% identical), rat Pclo (84% identical), mouse Pclo (83% identical), dog PCLO (65% identical), tropical clawed frog pclo (58% identical), guinea pig PCLO (57% identical), Caenorhabditis elegans cla-1 (19% identical). Paralogues in human: BSN (24% identical).
Diseases named in the same sentence as PCLO in open-access papers:
PCLO is named in the same sentence as 57 diseases in open-access papers, as found by Europe PMC text mining. Sharing a sentence is not in itself a finding about the gene and the disease. The quoted sentences say what the papers report.
depression (14 papers, 2010 to 2024). "An increasing number of studies have shown that the PCLO gene variant is related to major depressive disorder and is associated with gray matter volume reduction in the left temporal lobe." (PMID 38715006, 2024). "The single-nucleotide polymorphism (SNP) rs2522833 of PCLO has been reported to be associated with major depressive disorder in several studies." (PMID 34834409, 2021). "Several genetic studies have shown that SNPs of PCLO are associated with major depression, bipolar disorder, and drug abuse, while rare mutations of PCLO are associated with intellectual disability and pontocerebellar hypoplasia type III." (PMID 34834409, 2021). "The PCLO rs2522833 candidate polymorphism for depression has been associated to monoaminergic neurotransmission." (PMID 25379724, 2014). "After performing an association test with depression status as the dependent variable, the lowest P-value was found for in PCLO for rs2715147 at P = 1.5E-06 (OR = 0.79)." (PMID 24278217, 2013). "The piccolo (PCLO) gene, involved in monoaminergic neurotransmission, has previously been linked to depression in a genome-wide association study." (PMID 23620758, 2013). "Genome-wide association studies (GWASs) of major depressive disorder in humans also identified PCLO as a putative candidate gene." (PMID 24167553, 2013). "Overexpression of this C2A-domain causes a depression-like phenotype in mice, which makes the PCLO gene still an interesting candidate gene for MDD." (PMID 24278217, 2013). "The progression of CAD may aggravate through the crosstalk of the depression disorder with the PCLO gene variant and CAD." (PMID 38715006, 2024). "In addition to being related to depression, the risk (‘C’) allele in the PCLO rs2522833 polymorphism has also been associated with neural correlates of biased processing of emotional faces and memory bias." (PMID 25379724, 2014). "The SNP rs2522833 in the piccolo (PCLO) gene has been associated with current depression." (PMID 25379724, 2014). "Taken together, this suggests that PCLO genotype may increase the risk for developing or maintaining a depressive disorder by affecting the mood regulating capacity of the brain." (PMID 23620758, 2013). "The PCLO rs2715157 has been primarily established in MDD GWAS in Europeans, while IL18 rs187238 was associated with clinical depression, and a differential expression level of IL18 gene was related to rs187238 genotypes." (PMID 37510260, 2023). "It has been proposed that the PCLO rs2522833 polymorphism may be one of the genetic variants that increase the risk for depression by affecting the stress regulation capacity of the brain, possibly by altering monoaminergic neurotransmission, especially serotonin." (PMID 25379724, 2014). "Lastly, ENST00000423517, an isoform of PCLO, was associated with multiple traits in the cross-disorder (CDG) GWAS (meta-analysis of attention deficit hyperactivity disorder, bipolar disorder, major depression and SCZ, pLI = 1, 7q21.11)." (PMID 38036788, 2023). "A number of protein similarities are observed with Panel I including LRP1, a marker for migraine headache, and PCLO a possible marker for depression." (PMID 31026304, 2019). "As a result of linear regression analysis conducted in the DeprVUR sample controlling for sex, ethnicity, and age, we observed significant effects of the PCLO rs2715157 A-allele (β = 0.67, p = 0.03) and the IL18 rs187238 C-allele (β = 0.73, p = 0.03) on BDI-measured depression." (PMID 37510260, 2023). "A limitation is the difference in sex distribution between the two samples, as SNPs within the PCLO gene have been associated with depression in females and not in males." (PMID 25379724, 2014). "Previous studies found an association between depression and the PCLO rs2522833 polymorphism when studying current major depressive disorder, but not for sub-clinical levels of depression." (PMID 25379724, 2014).
depression (continued). "PCLO regulates methamphetamine-induced behavioral sensitization and depression-like behavior." (PMID 24167553, 2013). "Memory bias may not be strongly associated with the PCLO rs2522833 polymorphism, unlike other genes that have been associated with depression (e.g. BDNF, NR3C2)." (PMID 25379724, 2014). "The null-findings may therefore imply that the PCLO rs2522833 polymorphism is not related to emotional information processing that is associated with the susceptibility for depression." (PMID 25379724, 2014). "However, the demonstrated effect of PGS to evaluate individual liability to depressive personality in the DeprVUR sample is probably attributed to a significant impact of the PCLO rs2715157 and the IL18 rs187238 (p < 0.05) on depression score." (PMID 37510260, 2023). "In addition, we found emulsifier-treated animals had decreased expression of PCLO and increased expression of SGK1, which are known biomarkers of clinical depression, a disorder often characterized by HPA axis dysregulation." (PMID 35650224, 2022). "Major depressive disorder (MDD) has been linked to differences in the volume of certain areas of the brain and to variants in the piccolo presynaptic cytomatrix protein (PCLO), but the relationship between PCLO and brain morphology has not been studied." (PMID 28556829, 2017). "Moreover, it is unknown whether PCLO modulates negative bias and emotional memory in depression." (PMID 23620758, 2013).
melanoma (7 papers, 2018 to 2025). A malignant, usually aggressive tumor composed of atypical, neoplastic melanocytes. "Among the melanoma patients, the most frequently mutated genes were TTN, MUC16, BRAF, DNAH5, and PCLO." (PMID 40781483, 2025). "The most frequently mutated genes in human melanoma were those mutated in parental and dormant mouse cells (common genes), with up to 80% mutation rates for TTN, followed by PCLO (> 52%), DSCAM (approximately 40%), and OBSCN (approximately 34%)." (PMID 39223638, 2024). "The top 10 mutated genes in melanoma were TTN (72%), MUC16 (67%), DNAH5 (49%), PCLO (44%), LRP1B (38%), ANK3 (32%), DNAH7 (32%), ADGRV1 (35%), RP1 (33%), and BRAF (51%)." (PMID 33758620, 2021). "The top 10 mutated genes in 467 melanoma patients are TTN (72%), MUC16 (67%), BRAF (51%), DNAH5 (49%), PCLO (44%), LRP1B (38%), ADGRV1 (35%), RP1 (33%), ANK3 (32%), DNAH7 (32%)." (PMID 33072607, 2020). "Three neuronal-related genes (PCLO, PLXNA4, and EPHA7), and the gene encoding the leptin receptor (LEPR), all reported as mutated in melanoma at a variable frequency (37%, 11%, 16% and 8% of samples in TCGA cohort, respectively), were altered more frequently in R compared to NR patients." (PMID 37739939, 2023).
bipolar disorder (6 papers, 2013 to 2024). A disorder of the brain that causes unusual shifts in mood, energy, activity levels and the ability to carry out day-to-day tasks. "In contrast, another SNP, rs13438494, of PCLO is associated with bipolar disorder in a meta-analysis of the genome-wide association studies (GWASs) of bipolar disorder." (PMID 34834409, 2021). "A genome-wide association study showed that single-nucleotide polymorphisms (SNPs) in the PCLO gene were significantly associated with bipolar disorder and major depressive disorder." (PMID 34206873, 2021). "In conclusion, we identified three private rare pathogenic mutations in two PCM genes, BSN and PCLO, in three families with schizophrenia and bipolar disorder." (PMID 34834409, 2021). "We report the identification of three private rare pathogenic mutations of BSN and PCLO in three families with schizophrenia and bipolar disorder, respectively." (PMID 34834409, 2021). "The present study identified two missense mutations of PCLO in two families affected by bipolar disorder and schizophrenia, respectively." (PMID 34834409, 2021). "To the best of our knowledge, we are also the first to report the rare missense mutations of PCLO in patients with bipolar disorder and schizophrenia." (PMID 34834409, 2021). "One of the identified SNPs, rs13438494 in an intron of PCLO, was significantly associated with bipolar disorder in a large-scale meta-analysis of GWASs." (PMID 24167553, 2013). "The single nucleotide polymorphism (SNP) rs13438494 in intron 24 of PCLO was significantly associated with bipolar disorder in a meta-analysis of genome-wide association studies." (PMID 24167553, 2013). "Moreover, the rare missense variants Ser1535Leu and His5142Arg of PCLO were found in patients with bipolar disorder." (PMID 38715006, 2024). "Indeed, the SNP rs13438494 in intron 24 of PCLO, which disturbs the splicing pattern of PCLO mRNA to decrease expression, is associated with bipolar disorder." (PMID 34206873, 2021). "Furthermore, we identified the rare missense mutation Ser1535Leu of PCLO (piccolo presynaptic cytomatrix protein) in two sisters with bipolar disorder and another rare missense mutation, His5142Arg in PCLO, in a patient with schizophrenia." (PMID 34834409, 2021). "The molecular mechanisms underlying schizophrenia and bipolar disorder of these three rare mutations of BSN and PCLO identified in this study remain to be elucidated." (PMID 34834409, 2021). "A previous study demonstrated that the SNP rs13438494 (intron 24 of PCLO gene) could alter the splicing efficiency by creating or disrupting a splicing motif and ultimately resulted in bipolar disorder in affected people." (PMID 36015068, 2022). "Furthermore, differential expression of the PCLO gene transcript has been reported in the postmortem brains of patients with bipolar disorder and patients with schizophrenia." (PMID 34834409, 2021). "Our results increase the genetic and allelic heterogeneity of schizophrenia and bipolar disorder and suggest that BSN and PCLO may be considered risk genes for schizophrenia and bipolar disorder." (PMID 34834409, 2021).
liver cancer (6 papers, 2021 to 2025). An epithelial or non-epithelial malignant neoplasm that arises from the liver. "It has been reported that silencing PCLO can promote the invasion of liver cancer cell lines, and PCLO tends to be mutated in poorly differentiated liver cancer." (PMID 40699825, 2025). "PCLO mutations have been found in a number of human tumors, including gastric cancer, liver cancer, myeloid leukemia, diffuse large B-cell lymphoma and colon cancer." (PMID 40699825, 2025). "PCLO mutation commonly occurred in diverse cancers, such as esophageal cancer 59, liver cancer 60, and colon cancer." (PMID 36147475, 2022). "Recurrent mutations in PCLO were also discovered in diffuse large B-cell lymphoma and several solid tumors, including glioblastoma, liver cancers, and stomach adenocarcinoma." (PMID 33546774, 2021).
diffuse large B-cell lymphoma (4 papers, 2021 to 2025). "One study further reported that 17 of 49 patients with diffuse large B-cell lymphoma had nonsynonymous mutations in the PCLO gene." (PMID 36599976, 2023). "Additionally, comparing to the high-risk subgroup, the low-risk subgroup had a higher mutation rate (20% vs. 13%) for PCLO which is frequently mutated in tumors, including hepatocellular carcinoma and diffuse large B-cell lymphoma." (PMID 35205097, 2022). "The result showed 23 gene mutations, including MYD88, CD79B, CDKN2A, PIM1, RELN, PCLO, CREBBP, and so on, supporting the diagnosis of diffuse large B-cell lymphoma." (PMID 36599976, 2023). "The genetic test results of the left frontal parietal lobe lesion result revealed 23 gene mutations, including MYD88, CD79B, CDKN2A, PIM1, RELN, PCLO, CREBBP, and so on, supporting the diagnosis of diffuse large B-cell lymphoma." (PMID 36599976, 2023).
esophageal cancer (4 papers, 2019 to 2025). A primary or metastatic malignant neoplasm involving the esophagus. "The missense mutation rate of PCLO-E4090Q is 1.85% (3/162) in esophageal carcinoma." (PMID 34696226, 2021). "It has been reported that knockdown of PCLO in esophageal cancer cell lines could inhibit the subcutaneous reproductive capacity of cancer cells in nude mice." (PMID 40699825, 2025). "Interestingly, PCLO has recently been shown to exert an oncogenic role in esophageal cancer by interfering with EGFR signalling." (PMID 31308377, 2019).
esophageal squamous cell carcinoma (4 papers, 2020 to 2025). Esophageal squamous cell carcinoma (ESCC) is a type of esophageal carcinoma (EC) that can affect any part of the esophagus, but is usually located in the upper or middle third. "In recent years, PCLO has been discovered to be frequently mutated in cancers, such as esophageal squamous cell carcinoma (ESCC), gastric cancer and hepatocellular carcinoma." (PMID 40699825, 2025). "PCLO, as one of the most often altered or amplified genes in esophageal squamous cell carcinoma, encodes the Piccolo protein." (PMID 36599976, 2023). "Although the role of PCLO in cancer is unclear, it is the fifth most frequently mutated gene in esophageal squamous cell carcinoma (ESCC), which is consistent with our study." (PMID 33898301, 2020). "Furthermore, we observed that high PPAR activity correlated with mutations in the PCLO gene, which encodes a protein involved in synaptic function and has been linked to oncogenic signaling in cancer like EGFR signaling in esophageal squamous cell carcinoma." (PMID 39735727, 2024).
schizophrenia (4 papers, 2021 to 2026). A major psychotic disorder characterized by abnormalities in the perception or expression of reality. "In the third family, we identified another missense mutation (H5142R) of PCLO in a patient diagnosed with schizophrenia." (PMID 34834409, 2021). "For example, both schizophrenia and the FA of the left CP colocalized with the expression of the PCLO (ENSG00000186472) gene at chr7:82,503,409-82,616,835 (schizophrenia: PP.H4 = 0.828; left CP: PP.H4 = 0.819)." (PMID 41522603, 2026). "For example, both schizophrenia and the FA of the left CP colocalized with the expression of the PCLO gene." (PMID 41522603, 2026). "Together, these studies imply the involvement of PCLO in the pathogenesis of neurodevelopmental disorders, affective disorders, and schizophrenia." (PMID 34834409, 2021). "Furthermore, in a recent study, Nitta and colleagues reported that mice with suppression of PCLO expression in the medial frontal cortex showed schizophrenia-like behavioral impairments, including enhanced locomotor activity, impaired auditory prepulse inhibition, and cognitive dysfunction." (PMID 34834409, 2021). "The dopamine hypothesis, the current leading theory of the pathogenesis of schizophrenia, is supported by genetic studies indicating that single nucleotide variations (SNVs) related to dopaminergic transmission, such as DRD2, COMT, DISC1, and PCLO, are associated with a higher risk of schizophrenia." (PMID 34063598, 2021).
gastric cancer (3 papers, 2024 to 2025). A primary or metastatic malignant neoplasm involving the stomach.
Intellectual disability (3 papers, 2021 to 2025). "A 7q21.11 duplication comprising the PCLO gene was reported in an ARND patient (case number 326) with mild mental deficiency and growth retardation but without dysmorphism." (PMID 37189943, 2023). "Furthermore, a rare homozygous nonsense mutation has been found in a family with pontocerebellar hypoplasia type III, and deletion of the PCLO gene is thought to be involved in patients with intellectual disability." (PMID 34834409, 2021). "Notably, our patients did not have neurological symptoms or intellectual disability as described in other patients with rare PCLO mutations." (PMID 34834409, 2021).